CX3CL1 (C-X3-C motif chemokine ligand 1)
Diseases named in the same sentence as CX3CL1 in open-access papers (continued):
Sharing a sentence is not in itself a finding about the gene and the disease.
tumor (continued). "Overexpression of miR-125b inhibited TGCT growth by targeting CSF1 and CX3CL1, which are known tumour-derived chemokines involved in the recruitment of macrophages to the neoplastic sites." (PMID 36768818, 2023). "CX3CL1 secreted in the tumor microenvironment serves as a chemoattractant playing a critical role in metastasis of CX3CR1 expressing cancer cells." (PMID 37771579, 2023). "To observe the effect of MSC on CRC proliferation and sensitivity to αPD1 treatment after the knockdown of CX3CL1, we performed subcutaneous tumor analysis again." (PMID 36843945, 2023). "Secretion of soluble CX3CL1 can be part of a feedback loop to maintain a CX3CR1 driven immune-suppressive signaling program in the tumor." (PMID 37771579, 2023). "Immunofluorescence also showed that CX3CL1 was highly expressed in para-tumour, mainly around renal tubules." (PMID 35530333, 2022). "Our findings demonstrate the role of CX3CL1 in regulating the tumor immune microenvironment and its potential as a clinical prognostic marker for predicting the efficacy of immunotherapy." (PMID 36397015, 2022). "For primary tumor progression, CX3CL1/CX3CR1 played an important role in modulating inflammatory responses associated with macrophage survival and monocyte homeostasis." (PMID 35478937, 2022). "Our findings indicated the involvement of CX3CL1 in the occurrence and development of ccRCC by acting as a tumor suppressor." (PMID 36397015, 2022). "Reduced HLADR and CD86 are features of immunosuppressive monocytes in cancer, while loss of CX3CR1/CX3CL1 signalling in monocytes and TME can accelerate murine tumour growth." (PMID 36589727, 2022). "Additional studies aimed toward determining specific CCL2-, CCL7-, and CX3CL1-expressing areas and cell types within the tumor would need to be conducted to support these concepts." (PMID 36685592, 2022). "For example, in Mouse skin melanoma cancer, CX3CL1 kills tumour cells by chemotaxis of NK cells and T cells." (PMID 35530333, 2022). "Since this cell population also expresses CX3CR1, migration of bone marrow-derived cells from tumor-bearing Ccr2+/RFP/Cx3cr1+/GFP mice to soluble CX3CL1 was assessed." (PMID 36685592, 2022). "Overall, this study preliminarily characterized the potential role of CX3CL1 in the tumor immune microenvironment and in promoting the ferroptosis sensitivity of tumor cells." (PMID 36397015, 2022). "The IHC images and relative positive staining indicated that CX3CL1 was more expressed on adjacent tumor tissue than liver metastasis nodules." (PMID 35478937, 2022). "We determined that 15 cell types expressed CX3CL1 in peripheral blood, and 17 expressed it in the tumor." (PMID 36397015, 2022). "These genes encode for chemokines (CCL2/MCP-1; CX3CL1/Fractalkine; CCL7/ MCP-3) that modulate the immune response but have also frequently been found to be enriched in the tumor microenvironment." (PMID 35661927, 2022). "The overexpression of miR-125 in tumor cells leads to the inhibition of M-CSF and CX3CL1 production by tumors and in consequence the reduction of macrophages recruitment." (PMID 35053248, 2022). "Overall, these findings suggest that CX3CL1 can act as a therapeutic target in ccRCC by affecting ferroptosis and the tumor immune microenvironment." (PMID 36397015, 2022). "CX3CL1 was hypermethylated in tumours, and the degree of methylation was negatively correlated with mRNA expression." (PMID 35530333, 2022). "Paired analysis of samples showed that the expression levels of CX3CL1 in tumor tissues were significantly higher than those in the paired normal tissues." (PMID 36397015, 2022). "CX3CR1 and its ligand CX3CL1 play both a role in activating anti-tumor immunity and in promoting tumor formation and progression." (PMID 35223493, 2022). "We then used SingleR to identify the cell types expressing CX3CLR1, the receptor of CX3CL1, in the tumor and peripheral blood." (PMID 36397015, 2022).
tumor (continued). "Although soluble CX3CL1 did not stimulate migration of the MDSCs, a role for membrane attached CX3CL1 in firm adhesion of the cells to endothelium within the tumor vasculature remains a possibility." (PMID 36685592, 2022). "For tumor metastasis, emerging evidence suggested that CX3CL1 regulated metastasis of primary breast, lung, kidney, and prostate tumors." (PMID 35478937, 2022). "In summary, this study provides evidence for CX3CL1 contributing on the one hand to tumor growth and on the other hand to enhanced response to trastuzumab treatment in MDA-MB-453-transplanted HTM." (PMID 34070094, 2021). "The soluble CX3CL1, also called Fractalkine, has the capacity to attract different immune effector cells (e.g., T and NK cells) into the tumor environment." (PMID 34070094, 2021). "Once confirmed by the evaluation on human tumor samples, new approaches to enhance local CX3CL1 expression in combination with trastuzumab therapy should be tested in relevant pre-clinical models." (PMID 34070094, 2021). "The endothelial-derived CX3CL1 has been shown to be responsible for tuning immunologically cold tumor into hot tumor." (PMID 34572138, 2021). "Here we explored the impact of CX3CL1 on trastuzumab treatment efficiency and immunological mechanism involved in a humanized tumor mouse model." (PMID 34070094, 2021). "Overall, this study provides evidence for CX3CL1 contributing on the one hand to tumor growth and on the other hand to enhanced therapy response to trastuzumab treatment in MDA-MB-453-transplanted HTM." (PMID 34070094, 2021). "On the other hand, DCs constitutively express CX3CR1 34, so it would be very interesting to evaluate in a carcinogenesis model, if immature DCs can be recruited into the tumor by exogenous CX3CL1." (PMID 33391453, 2021). "A study in mice showed that local tumoral production of CX3CL1 promoted the anti-tumor response by recruitment of NK cells." (PMID 34503058, 2021). "A unique class of chemokines-the CX3C family has been reported playing a critical role in tumor immune regulation, in which CX3CL1 is the only member." (PMID 34671562, 2021). "At the same time, CX3CL1 has been reported to regulate the metastasis of various tumours through MAPK/ERK and PI3K/AKT signalling pathways." (PMID 33191645, 2021). "The RNA-Seq results, and protein expression results are consistent with a previous clinical prognostic analysis and in vivo and in vitro experimental results, which together indicate the tumor-promotive effect of CX3CL1 in BCa." (PMID 34671562, 2021). "For this reasons, MDA-MB-453 was chosen for the transfection experiments to identify the impact of CX3CL1 expression on tumor growth, metastases formation and treatment efficiency of trastuzumab and ADAM inhibitors." (PMID 34070094, 2021). "We found that cabozantinib treatment significantly upregulated CCL11, CCL12, CXCL12, CCL8 and CX3CL1 in the tumor microenvironment." (PMID 33954115, 2021). "Mechanistically, we found that cabozantinib treatment induced expression of neutrophil-related chemokines (CCL11 and CXCL12) and T cell-related chemokines (CCL8 and CX3CL1) in the tumor microenvironment." (PMID 33954115, 2021). "CX3CL1 reportedly promotes T cell aggregation in tumor tissue and is positively correlated with patient prognosis." (PMID 33954115, 2021). "CX3CL1 is commonly expressed in the tumor microenvironment and is capable of inducing cell migration in both tumor cells and immune cells with anti-tumor activity." (PMID 33391453, 2021). "Our results demonstrated that CX3CL1/ICAM-1 signaling, which underlies tumor cell-endothelium interactions, constituted a vicious feedback cycle between circulating NSCLC cells and the bone microenvironment to promote NSCLC spinal metastasis." (PMID 33754027, 2021). "NK cell-mediated trafficking towards tumor cell-infiltrated lungs in mice was shown to be dependent on the CX3CL1/CX3CR1 axis." (PMID 34503058, 2021).
tumor (continued). "Studies have suggested that CX3CL1 exerts its tumor-suppressive effect by activating immune cells, including natural killer T cells, and inhibiting tumor cell aggregation and adhesion." (PMID 34671562, 2021). "Transendothelial migration is a crucial step in tumor metastasis; thus, the effect of CX3CL1 on NSCLC cell transendothelial migration was investigated." (PMID 33754027, 2021). "It has been reported that chemokine CX3CL1 can regulate various tumours by binding to its unique receptor CX3CR1." (PMID 33191645, 2021). "Among these chemokines, C‐X3‐C motif chemokine ligand 1 (CX3CL1) has been regarded as an essential mediator in tumor metastasis." (PMID 33754027, 2021). "This cycle is based on CX3CL1/ICAM-1-mediated NSCLC cell-VBMEC interactions resulting in enhanced tumor cell aggressiveness and adhesion, improved VBMEC permeability, and increased NSCLC cell transendothelial migration through several signaling pathways." (PMID 33754027, 2021). "It was reported that high expression of CX3CL1 can induce tumor cell proliferation and promote the transformation of the cell cycle to S phase in gastric cancer." (PMID 34671562, 2021). "In the transgenic MMTV-ERBB2/neu mouse model, 30 days of TMI-1 treatment has been described to reduce tumor growth, but Tardáguila described a downregulation of CX3CL1 in the tumors of these mice compared to the healthy tissue." (PMID 34070094, 2021). "An increased tumor growth under the influence of CX3CL1 has also been described for MDA-MB-453 and HT 29 transplanted SCID mice during the first period of engraftment (publication under review)." (PMID 34070094, 2021). "Tumor cells upregulate miR-561-5p, which in turn inhibits the production of CX3CL1 and subsequently reduces NK cell recruitment to the tumor." (PMID 34017344, 2021). "In humanized tumor mice, which show a coexistence of human tumor and human immune system, CX3CL1 overexpression resulted in a slightly enhanced tumor growth." (PMID 34070094, 2021). "The results above showed that cabozantinib treatment increased the expression of CCL8 and CX3CL1 in the tumor environment, which is important for T cell migration." (PMID 33954115, 2021). "In human samples of spine metastasis, they found that upregulation of CX3CL1 is independent from the primary tumor." (PMID 34063821, 2021). "Treatment with the NF-κB inhibitor Bay11-7085 (10 μM) significantly minimized tumor cell-induced elevations of CX3CL1 expression." (PMID 33754027, 2021). "We found that after CX3CL1 was inhibited, tumor cell proliferation, cell malignant transformation, tumor cell interphase, and differentiation of stem cells were significantly inhibited, and tumor cell apoptosis was significantly increased." (PMID 34671562, 2021). "The tumor cells secreted a few C/Cs on the panel, including exclusive secretion of IL-11, and shared secretion of CX3CL1, LIF and TIMP-1 with the fibroblasts." (PMID 34572807, 2021). "The CX3CL1/CX3CR1 axis has both tumor-promoting and suppressive effects in cancer progression, resulting in either favorable or unfavorable prognosis depending on the cancer types." (PMID 31991604, 2020). "It has been shown that CX3CR1+ monocytes are recruited to the tumor cell aggregates in response to tumor-derived CX3CL1, where they can directly engage cancer cells or secrete CCL3, CCL4 and CCL5 to activate natural killer cells to kill CTCs." (PMID 33414786, 2020). "CX3CL1 functions as an adhesion molecule for arresting circulating tumor cells in spine microvasculature." (PMID 32390803, 2020). "This is a previously unreported mechanism by which CX3CL1 contributes to the vertebral micro-vascular barrier dysfunction and promotes tumor cell TEM to the spine." (PMID 32390803, 2020). "Mature dendritic cells show CX3CL1 expression, and in the tumor niche, this enables the migration of NK cells and T cells to mature dendritic cells." (PMID 32466280, 2020).
tumor (continued). "Our previous study found that vertebral spongy bone was rich in CX3CL1 and that CX3CL1 can attract fractalkine receptor-expressing tumor cells to the spine." (PMID 32390803, 2020). "The concentration of 90 ng/mL (3 nM) occurs in inflammatory reactions, and thus, the nature of the action of CX3CL1 on inflammatory reactions in macrophages in a tumor depends on the intensity of these reactions." (PMID 32466280, 2020). "It seems that this process in the tumor involves VEGF-A, a growth factor causing GATA3 to attach to the CX3CL1 gene, and thus, reducing its expression." (PMID 32466280, 2020). "An increase in CX3CL1 expression in a tumor is correlated with the anti-cancer response of the immune system—the accumulation of anticancer CD4+ T cells, CD8+ T cells, dendritic cells and NK cells in a tumor." (PMID 32466280, 2020). "One such site is a tumor, a place of intensive immunological reactions and high expression of CX3CL1." (PMID 32466280, 2020). "With regard to the possible involvement of HPK1 in the regulation of T cell trafficking to the tumor, CX3CL1 transcripts are found to be elevated in tumor draining lymph nodes of tumor-bearing K46M HPK1 mice." (PMID 32896273, 2020). "In contrast, CX3CL1/CX3CR1 has been proven to induce tumor growth, proliferation, and apoptosis resistance through activating the AKT/NF-κB and JAK/STAT signalling pathways in PDAC." (PMID 31991604, 2020). "RNA profiling of microenvironment-related genes revealed increased expression of markers for TAMs and resident microglia (Aif1, Itgam, Cd68 and Cx3cl1), and macrophage M1/M2 polarisation (Cd80 vs. Cd163) in knockdown tumours." (PMID 33339831, 2020). "NK cells, T cells, and dendritic cells are involved in CX3CL1‐induced antitumor immunity, and macrophages exhibit tumor‐promoting characteristics different from circulating macrophages." (PMID 32799418, 2020). "Chronic hypoxia in a tumor impairs the normal immune response; in particular, it abolishes the effect of proinflammatory cytokines on CX3CL1 expression, which inhibits the recruitment of anticancer immune system cells into the tumor niche." (PMID 32466280, 2020). "We found that only incubating VMECs with CX3CL1 increased the TEM of tumor cells but that pre-inhibition of Src/P115-RhoGEF/ROCK signaling in the VMECs significantly reversed CX3CL1-induced VMECs barrier hyperpermeability and the high rate of tumor cell TEM." (PMID 32390803, 2020). "Taken together, our findings indicate that HCC cell‐derived CX3CL1 contributes to tumor infiltration by platelets, which in turn promotes apoptosis of HCC cells." (PMID 32799418, 2020). "The results of this study and our previous study indicate that in addition to its chemotaxis, CX3CL1 plays a critical role in regulating vertebral micro-vascular barrier function and tumor cell TEM." (PMID 32390803, 2020). "For this reason, many studies show a correlation between increased expression of CX3CL1 and the number of lymphocytes in the tumor and positive patient prognosis." (PMID 32466280, 2020). "Recently, CX3CL1 (fractalkine) was recognized as the principal endothelial-derived chemokine responsible for turning immunologically cold tumor into a hot tumor." (PMID 32958605, 2020). "Overexpression of miR-125b in testicular tumor cells significantly reduced the TAMs population at tumor site via inhibiting the production of tumor-promoting cytokines such as CSF-1 and CX3CL1." (PMID 32992449, 2020). "High levels of CX3CL1 is known to be associated with an increased number of CD8+ and CD4+tumor infiltrating lymphocytes (TILs) in colorectal cancer and is a good prognostic indicator of survival." (PMID 32896273, 2020).
tumor (continued). "Physical contact between Schwann cells and tumor cells is necessary to potentiate the process of tumor invasion, by induction of specific chemokines, such as CX3CL1 and its receptor CX3CL1." (PMID 31921388, 2019). "CX3CL1 is also capable of recruiting tumor-suppressive immune cells that express the CX3CR1 receptor such as NK cells and cytotoxic T lymphocytes (CTLs)." (PMID 31482487, 2019). "A possible involvement of CX3CR1 in the cross talk between neoplastic B cells and the tumor microenvironment has been proposed since CX3CL1 and CX3CR1 are co-expressed on different types of B malignant cells." (PMID 30845779, 2019). "CX3CL1 overexpression or miR-561-5p knockdown in HCCLM3 cells significantly suppressed tumor volume, reduced the rate of lung metastasis, and enhanced NK cells infiltration." (PMID 31367257, 2019). "The CXCR3 and CX3CR1 chemokine receptor ligands CXCL9-11 and CX3CL1, respectively, are mainly responsible for the tumor-suppressive lymphocytic infiltration into the tumor micromilieu." (PMID 31482487, 2019). "Previous research has found that high expression levels of CX3CL1 in tumor cells can induce tumor-infiltrating CD8+ T cells, dendritic cells, and activated natural killer cells to exert antitumor immune activity, thus inhibiting tumor growth." (PMID 30718976, 2019). "By RNA profiling, Western blot and luciferase reporter assay, we further observed that miR-125b directly regulated tumor cell-derived chemokine CSF1 and CX3CL1, which are known to control the recruitment of TAMs to tumor sites." (PMID 30237497, 2018). "If in the tumor microenvironment there are also other chemokines (i.e. in addition to CX3CL1/fractalkine), then it results in the inhibition of US28-dependent monocyte and macrophage migration." (PMID 29467963, 2018). "CX3CR1 genetically modified T cells transferred into CX3CL1 producing colorectal adenocarcinoma tumor bearing mice displayed enhanced tumor infiltration and anti-tumor responses." (PMID 30420855, 2018). "Altogether, these results demonstrated the crucial feature of VEGF-A in inflammatory programming of tumour vasculature, repressing CX3CL1 expression and enabling extravasation of proangiogenic monocytes to solid tumours." (PMID 29367702, 2018). "Given the existence of NFκB and GATA3 binding sites also in the mouse Cx3cl1 gene, we further investigated the binding of these transcription factors with Cx3cl1 in tumour endothelial cells and eventual involvement of VEGF-A signalling in this process." (PMID 29367702, 2018). "We found that NFκB interaction with Cx3cl1 was higher in endothelial cells of SKBR7 grafts compared to DLD1 tumours." (PMID 29367702, 2018). "This is in line with our data showing the significant induction of CX3CL1 after nivolumab treatment and its downregulation at tumor progression." (PMID 30108590, 2018). "A recent study proposed that CX3CL1 mediates extravasation of mouse patrolling monocytes in lung vasculature during tumour metastasis." (PMID 29367702, 2018). "Expression of the angiogenic factor VEGF and the inflammatory cytokine TNF by tumour cells enables HPMo extravasation by inducing GATA3-mediated repression of CX3CL1 expression." (PMID 29367702, 2018). "It is well-demonstrated that CSF1 and CX3CL1 control the recruitment of TAMs into tumor microenvironment." (PMID 30237497, 2018). "Conversely, shRNA-mediated depletion of Cx3cl1 in SCT cells significantly reduced tumour growth in WT syngeneic immunocompetent mice, but not in immunodeficient mice." (PMID 29234059, 2017). "It is true that tumor metastases are extremely complex, and CX3CL1 needs other molecules to work in a coordinated fashion to induce spinal metastases." (PMID 28122354, 2017). "Some studies concluded that the greater the CX3CL1 expression, the better the prognosis, which is in accordance with the previously suggested role of CX3CL1 in enhancing anti-tumor immunity." (PMID 28122354, 2017).